HIF1A (hypoxia inducible factor 1 subunit alpha)
Diseases named in the same sentence as HIF1A in open-access papers (continued):
Sharing a sentence is not in itself a finding about the gene and the disease.
tumor (continued). "Thus, increased HIF-1α promotes ECM remodeling through regulation of collagen deposition by tumor cells and upregulation of metalloproteinases and collagen-modifying enzymes in stromal cells." (PMID 36076905, 2022). "However, cancer overcomes the adverse influence of hypoxia on tumor growth partially by inducing HIF1A expression." (PMID 35739524, 2022). "Additionally, the TME of HGG is generally hypoxic, leading to upregulation of vascular endothelial growth factor (VEGF) and hypoxia-inducible factor-1 alpha (HIF1a) and therefore enhanced migration of MDSCs to the tumor." (PMID 36186781, 2022). "HIF-1α is upregulated in BE and correlates with the inflammation, but since it is not upregulated in dysplasia or neoplasia, it is thought to be an initial event to neoplasia and inflammation." (PMID 35511379, 2022). "Additionally, the high mitophagy subtype (cluster C ) shows high levels of HIF1A expression, indicating that the tumour in cluster C has a strong hypoxic environment." (PMID 35938160, 2022). "The exosomal package of HIF-1α for delivery within the hypoxic TME enhances tumor cells to evade degradation, as they utilize exosomes as a safe transporter of HIF-1α to the recipient cells, where it regulates its transcriptional targets and propagates hypoxic signaling." (PMID 36233088, 2022). "Interestingly, although VEGF expression is induced by HIF-1α during hypoxia, its expression can also be modulated by tumor integrins, resulting in efficient tumor angiogenesis under normoxic conditions." (PMID 35198082, 2022). "Hif-1α helps to regulate angiogenesis, tumor growth, metastasis, and metabolic reprograming." (PMID 36080307, 2022). "HIF1A is one of the main regulators of tumour cell adaptation to the hypoxic microenvironment." (PMID 35023280, 2022). "Tamoxifen and baicalein combinatorially reduced the levels of HIF-1α in tumor tissues." (PMID 35955525, 2022). "Interestingly, fluorescence-guided surgery on GBM sections further revealed higher KDM5C and HIF1A levels in the tumor rim niche compared to the adjacent tumor margin, indicating a regionally restricted hyperactivity of this regulatory axis." (PMID 36142158, 2022). "In addition to hydroxylation of Pro564, Pro402, and Asn803, lysine (Lys532) in the oxygen-dependent degradation domain is blocked by acetyltransferase arrest-defective 1 (ARD1) to promote tumor pVHL binding, leading to HIF-1α instability." (PMID 36003773, 2022). "Recent studies have shown that Piezo1 can induce tumor angiogenesis in an HIF-1α-dependent manner." (PMID 36230880, 2022). "One study has demonstrated that calcitriol-mediated antiproliferative effects on tumor-derived endothelial cells (TDEC) are VDR dependent and that loss of VDR in knockout models can lead to an increase in HIF-1α, VEGF, Ang1, and PDGF-BB levels and subsequent abnormal tumor angiogenesis." (PMID 35406562, 2022). "In addition, β-carotene was found to inhibit the spread of tumour cells by dysregulation and lower expression of HIF-1α, VEGF, and GLUT1." (PMID 35276890, 2022). "The results revealed that the frequency of positive staining for HIF-1α (i.e. HIF-1α+ cells) was negatively correlated with that of positive staining for CD31 (i.e. CD31+ cells) in tumor stroma cells, indicating that TME blood vessels provide oxygen to tumor cells nearby." (PMID 35896535, 2022). "FN seems to promote metastasis and is a well-known marker of the mesenchymal phenotype, which points toward the possibility that HIF1α overexpression under hypoxia might result in re-expression of FN in tumor cells, which promotes EMT." (PMID 36497411, 2022). "Most of the key glycolytic enzymes are affected by MYC and HIF-1α in tumor glycolysis metabolism." (PMID 36532721, 2022). "Notably, inhibition of PD-L1 on tumor cells by LEM was preserved in mice with conditional knockout of Hif1a in T cells." (PMID 35239514, 2022). "Under hypoxic conditions, HIF1α will accumulate inside tumor cells." (PMID 35912204, 2022).
tumor (continued). "In addition, CD133-expressing colorectal cancer cells exhibited increased HIF-1α expression and accentuated tumor cell migration during hypoxia compared to CD133-negative cells." (PMID 35870078, 2022). "We also showed that chrysin inhibits SPHK-1 and HIF-1α expression in tumor tissues." (PMID 36139362, 2022). "Also, miR-155 is described as a direct inhibitor of HIF-1α, and thus, being a regulator of various signaling pathways, miR-155 functions as an oncomiR and a tumor suppressor." (PMID 36012588, 2022). "We analyzed the expression and function of MT1JP in TNBC and found that MT1JP was downregulated in TNBC and may play a tumor suppressive role by upregulating miR-138, which can direct target HIF-1α." (PMID 35703312, 2022). "Whether TIMP‐1 expression is regulated by hypoxia in hASC‐co‐cultured tumor spheroids, and whether hypoxia‐related factors other than HIF‐1α might affect it remains to be elucidated." (PMID 35600659, 2022). "Hypoxia is a common feature of the tumor microenvironment, and it could inhibit tumor cell proliferation and induce apoptosis by affecting the expression of hypoxia-induciblefactor-1α (HIF-1α) and the production of oxygen species (ROS)." (PMID 36353706, 2022). "It has been reported that inhibition of HIF-1α by siRNA could reduce tumor growth, and hypoxic tumor microenvironment (TME) enhances tumor angiogenesis and progression." (PMID 35607406, 2022). "Upregulated HIF-1α expression in tumor cells and immune cells is characteristic of the TME." (PMID 35927985, 2022). "These cells may secret various cytokines, such as VEGF, CXCL1, CXCL2, IL-1 and IL-6 via hypoxia-inducible factor-1α (HIF-1α) and NF-κB pathways, leading to a tumor-promoting TME." (PMID 35444953, 2022). "Nevertheless, the relation between tumor stage and HIF1α in BC is unclear." (PMID 36140796, 2022). "Tumor cells promote HIF-1α synthesis by activating PI3K and MAPK signaling pathways." (PMID 35493517, 2022). "Conversely, inhibition of HIF-1α has been shown to enhance the anti-tumor activity of T-cells." (PMID 36077845, 2022). "In fact, both SP1 and HIF-1α positively regulate NRP1 expression in tumor cells." (PMID 35600336, 2022). "Tumor hypoxia was then examined with hypoxia-inducible factor (HIF)-1α staining (green signals)." (PMID 35697679, 2022). "Likewise, TIM-3 also activates the PI3K/mTOR signaling pathway, resulting in the accumulation of hypoxia-inducible factor 1-alpha (HIF1α), which can induce programmed cell death-ligand 1 (PD-L1) expression in tumor cells to escape adaptive immunity." (PMID 35720276, 2022). "HIF1α is a key component of HIF1, a transcription factor that senses low cellular oxygen levels and regulates the expression of genes implicated in glucose metabolism, angiogenesis, and other signaling pathways that are critical to tumor growth." (PMID 35198082, 2022). "However, transcriptional effects of HIF-1α have been reported in rapidly proliferating tumor cells even at >1% intracellular O2, suggesting the role of FIH-1." (PMID 35592530, 2022). "HIF-1α inhibitor combined with paxilitaxel blocked autophagy and augmented the anti-tumor effects." (PMID 36311748, 2022). "In various tumors, increased HIF-1α also plays a role in tumor growth and progression." (PMID 35250391, 2022). "HIF-1α not only plays a crucial role in the adaptation of tumor cells to hypoxia but also regulates different biological processes, including cell proliferation, survival, cellular metabolism, angiogenesis, metastasis, cancer stem cell maintenance, and propagation." (PMID 36014432, 2022). "Moreover, the tumor growth rates of E0771 with Hif1a knockdown were also significantly reduced in immunocompetent versus immunodeficient recipients." (PMID 35239514, 2022).
tumor (continued). "Studies have shown that the functions and polarization of M2 macrophages could be directly regulated by lactate in the tumor microenvironment (TME) via hypoxia inducible factor-1 (HIF-1α)-dependent metabolic reprogramming." (PMID 35328434, 2022). "In addition, IL-15 activates STAT3 pathway and IL-2 activates PI3K/mTOR signaling, which then stabilize HIF-1α expression, and maintain natural defense against microbial infection and tumor development." (PMID 36761171, 2022). "However, in regard to the hypoxic microenvironment formed by the rapid proliferation of tumor cells, there have been studies on the effects of HIF-1α/ERRα interactions with glycolysis and angiogenesis." (PMID 35800058, 2022). "Rapid tumor cell proliferation generates hypoxia in local tumor tissue, which activates and upregulates hypoxia-inducible factor 1α (HIF-1α), resulting in the upregulation of the expression of pro-angiogenic factors, such as vascular endothelial growth factor (VEGF), to promote angiogenesis." (PMID 36172186, 2022). "The predominantly metastatic tumours in our cohort contained more frequent mutations in several genes such as SETD2, APC, KDM5C, HIF1A, RBM10, TRAK1 and FBXW7, while we detected lower mutation rates in VHL compared to the primary tumours analysed in the TCGA study." (PMID 35231161, 2022). "The central role of HIF-1α in tumor pathogenesis is thus evident." (PMID 36671757, 2022). "HIF1α may participate in the regulation of glycolysis and oxidative phosphorylation during the tumor progression." (PMID 35153295, 2022). "For example, lactate can stimulate the nuclear factor kappa B (NF-κB)/ Interleukin-8 (IL-8) or the HIF-1α signaling pathway to promote tumor angiogenesis and growth when it is released from tumor cells through MCT4 and imported into endothelial cells via the MCT1." (PMID 36612084, 2022). "Moreover, it induces the M2 polarization of macrophages and promotes tumor growth through mechanisms by involving the hypoxia-inducible factor 1-alpha (HIF-1α)." (PMID 36246596, 2022). "Compared to ICG/PDT, Perftoran®/ICG/PDT led to higher photocytotoxicity, inhibited pimonidazole hypoxia adducts, inhibited HIF-1α/β concentrations, induced the expression of tumor-suppressing miRNAs let-7b/d/f/g, and strongly inhibited the pro-hypoxia miRNA let-7i." (PMID 35370727, 2022). "The tumor-promoting mechanisms of TME include: 1) HIF-1α nuclear transport pathway: Hypoxia inducible factor-1 (HIF-1) is a key transcriptional activator responsible for regulating target genes that contribute to survival and growth of cells in hypoxia condition." (PMID 35711646, 2022). "Moreover, tumor volume and weight decreased after HIF1α or HIF2α knockout with the same temozolomide treatment." (PMID 34976166, 2022). "In addition, inhibition of HIF1α by shRNA was shown to result in decreased tumor-induced angiogenesis and reduced tumor burden in in vivo models of MM." (PMID 35053409, 2022). "V(Hb)@DOX could effectively limit the recruitment of CD163+ M2-type macrophages and improve tumor hypoxia by reducing HIF-1α expression." (PMID 36311793, 2022). "HIF-1α protein is highly expressed in most tumor tissues and the corresponding metastases." (PMID 35222641, 2022). "Hence, PLOD2 activation induced by HIF-1α is especially critical to ultimately increase fibrillar collagen formation and tumor stiffness." (PMID 36140753, 2022). "Knockout of Glut‐1 and HIF‐1α could inhibit glucose uptake in tumour tissues of xenograft, and block the enhanced glucose uptake ability of tumour tissue induced by radiotherapy." (PMID 35415942, 2022). "Combinations of HIFα inhibitors, particularly HIF-1α inhibitors, with immune checkpoint blocking antibodies may represent a novel approach to boost the overall anti-tumor immune profile in patients and thus enhance outcomes after SABR." (PMID 35805044, 2022). "VDU2 can interact with HIF-1α, a tumor suppressor, to deubiquitinate and stabilize HIF-1α." (PMID 36386843, 2022).
tumor (continued). "HIPK2 promotes the degradation of HIF-1α, suppressing tumor growth and progression of HCC." (PMID 35629368, 2022). "The purpose of this study was to elucidate whether NBO2 water could act as a radiosensitizer via regulation of HIF-1α in a tumor-bearing mouse model and whether it has any side effects consistent with previous in vitro experiments." (PMID 35743281, 2022). "Chetomin is a metabolite complex produced by several fungi of the genus Chaetomium that can target and block the formation of the HIF-1α/p300 complex and inhibit the transcriptional activity of genes involved in the proliferation, survival, and development of tumor cells in response to hypoxia." (PMID 36139386, 2022). "Overall, these results demonstrated that GSK3α-inducing tumor angiogenesis was dependent on HIF1α." (PMID 35292059, 2022). "Thus, pharmacologic or genetic targeting of HIF-1α in tumor cells alone can confer an immunotherapeutic effect." (PMID 35239514, 2022). "In addition, experiments demonstrated that VE-821 can inhibit ATR-mediated signaling under hypoxia, thereby inhibiting the stability of HIF-1α and increasing the sensitivity of tumor cells to radiotherapy." (PMID 36139386, 2022). "Stage IIA, when the tumor has grown large but not yet metastasized to the lymph largely contains cluster 5 fibroblasts, which have high HIF1A, as well as ARNT that encodes HIF-1β subunit of the HIF complex." (PMID 35565326, 2022). "HIF-1a expression is high in neoplasia, and it is responsible for the suppression of tumor cells by inducing NO synthesis, CD 47, PD-L1, and HLA-G overexpression in the tumor microenvironment, overregulation of ADAM 10 metalloproteinase expression, and adenosine increases." (PMID 36294785, 2022). "These evidences suggest that in the HNSCC TME, hypoxia might promote the migration of pDCs into tumor tissues through the HIF‐1α/SDF‐1/CXCR4 pathway." (PMID 34964283, 2022). "Indeed, HIF-1α controls a highly complex network connecting several signaling pathways and various overlapping mechanisms in tumor cells and other cells in the tumor microenvironment." (PMID 35795658, 2022). "In vivo, HNK inhibited tumor growth and HIF-1α-mediated glycolysis." (PMID 35350760, 2022). "The production of miRNAs in tumor-derived exosomes can be regulated by HIF-1α or HIF-2α." (PMID 36071472, 2022). "Hypoxic conditions prevent HIF-1α from being degraded in proteasomes via the von Hippel Lindau protein-mediated pathway, leading to its accumulation in cancer cells and its excretion into tumor stroma." (PMID 35205136, 2022). "In addition, HIF-1α is one of the critical transcription factors in tumor progression, and cancer targeted therapy." (PMID 36059961, 2022). "Under hypoxic conditions, the expression of CAIX (carbonic anhydrase IX) regulated through EGFR/STAT3/HIF-1α axis significantly increased in GBM, contributing to the polarization of tumor-associated monocytes/macrophages (TAM) toward a more tumor-supportive phenotype." (PMID 35600367, 2022). "This indicates that HIF-1α can promote tumor proliferation in vivo." (PMID 35664561, 2022). "HIF1α overexpression was seen in all three WT elements, predominantly in the tumor stroma." (PMID 36818371, 2022). "HPLC showed that the polyamine content in the tumor tissue of the overexpression group HIF1α OE was higher than that of the wild group HIF1α (+/+), and higher than that of the knockdown group HIF1α (-/-), but the content of polyamines in intestinal mucosa was the opposite." (PMID 35912204, 2022). "Functionally, both CKAP2 and HIF-1α at least partially mediated the pro-tumor activities of DLEU1." (PMID 35853854, 2022). "Moreover, succinate was reported to promote TAM polarization through upregulation of HIF-1α and takes part in the induction of IL-6 secretion to the tumor microenvironment, which was pivotal for cell migration in an in vitro model." (PMID 35205136, 2022). "The proportion of HIF-1α-positive cells in tumor tissues of mice in the four groups was compared." (PMID 35693265, 2022).
tumor (continued). "Moreover, VEGF/FLT1 activates HIF-1α via activation of ERK1/2 resulting in an alteration in VEGF level in tumor cells." (PMID 36014432, 2022). "Moreover, HIF-1α affects chemo/radiosensitivity via the regulation of genes that are related to tumor metabolism." (PMID 36551540, 2022). "Moreover, the expression of HIF-1α also regulates the glycolytic metabolism, migration, and invasion in tumor cells to adapt to hypoxic conditions for survival." (PMID 35631488, 2022). "In a tissue environment that lacks oxygen supply, tumor cells adapt their metabolism via induction of hypoxia-inducible factor (HIF)-1α, a central TF mediating hypoxic adaptation and tumor growth through various mechanisms including glucose metabolism, angiogenesis, cell survival, and apoptosis." (PMID 35205770, 2022). "Inhibition of HIF-1α down-regulated expression of pro-inflammatory factors IL-10, IL-12, PGE2, S-180, TNF-α, and abrogated memory CD4+, CD8+ T cells-mediated suppression of tumor-associated macrophages (TAM)." (PMID 36761171, 2022). "Second, HIF-1α has a stronger inhibitory effect on tumor growth after silencing." (PMID 36591450, 2022). "HIF-1α activation has been found to have a significant impact on cancer cell metabolism as it influences the expression of several genes leading to increased glycolysis and impaired mitochondrial function in tumor cells." (PMID 35432450, 2022). "Furthermore, HIF1A-induced miR-210 expression in tumor-related MDSCs is higher than that in splenic MDSCs." (PMID 35659268, 2022). "Thus HIF-1α has multiple ways to activate tumour progression and induce resistance of tumour cells to a range of therapies." (PMID 36076967, 2022). "Therefore, HIF-1α has been considered a promising target to interfere with many aspects of tumor progression." (PMID 36551540, 2022). "Overall, these results highlight the pleiotropic nature of the acute hypoxic response, with tumor-suppressive and oncogenic roles in different contexts through the action of diverse HIF1A targets, while also revealing a prominent role for hypoxia-induced ECM remodeling in cancer progression." (PMID 33654095, 2021). "Additionally, hypoxia, TGF‐β1 and tumour cell CM up‐regulated the expression of HIF‐1α in fibroblasts, inducing the conversion of fibroblasts into CAFs." (PMID 33943003, 2021). "Notably, applying HIF-1α LNA to treat the tumor derived from HIFAL null cancer cells significantly suppresses tumor growth in mice." (PMID 33637716, 2021). "HIF-1α regulates the expression of proangiogenic genes, specifically vascular endothelial growth factor and the angiopoietin/Tie-2 system in vitro in primary human endothelial cells, thereby, improving tumor blood flow." (PMID 34064873, 2021). "Moreover, genetic deletion of pancreas-specific HIF-1α drastically accelerates KrasG12D-driven PDAC neoplasia by enhancing B lymphocyte infiltration, indicating a protective role of HIF-1α in PC initiation." (PMID 33436044, 2021). "PDK1 is a direct target of HIF-1α in cancer cells under both hypoxic and normoxic conditions, and its downregulation by short hairpin RNA reverts the glycolytic phenotype, inhibits tumor growth and reduces invasiveness in several tumor cell lines." (PMID 34439291, 2021). "ONBs reverse hypoxia and suppress HIF-1α activity in tumor cells." (PMID 33659251, 2021). "Indeed, Hif1a specific deletion in NK cells drives tumor rejection in NK cell-sensitive solid tumor models, and it is associated with increased NK cell activation in terms of IFNγ production and cytoxicity." (PMID 33546248, 2021). "In a hypoxic tumor microenvironment, HIF1A signaling is activated and activated HIF1A signaling can regulate the biological responses related to tumorigenesis and progression (e.g. tumor cell survival, proliferation, metastasis, and angiogenesis) in multiple cancers including SC." (PMID 34621671, 2021).